CRABP2 (cellular retinoic acid binding protein 2)
Diseases named in the same sentence as CRABP2 in open-access papers (continued):
Sharing a sentence is not in itself a finding about the gene and the disease.
tumor (continued). "Considering the limited research on CRABP2 and tumor immunity, we attempted to apply bioinformatics analysis to explore the potential significance of CRABP2 for tumor immunotherapy." (PMID 38186580, 2023). "CRABP2 was identified as a TMB-related gene in SKCM, and the significance of CRABP2 for tumor prognosis was attempted to analyze from two immune-related aspects: TMB and immune infiltration." (PMID 38186580, 2023). "In normal lung tissue adjacent to the tumor, CRABP2, DHCR24, and AK4 were observed in bronchial epithelial cells, but not in alveolar pneumocytes." (PMID 37004157, 2023). "The correlation between CRABP2 and checkpoint molecules in all tumor types were displayed in a heat map." (PMID 38186580, 2023). "Correlation analysis showed that CRABP2 expression was related to tumor diameter, pT stage, pN stage, and pTNM stage (P < 0.05)." (PMID 36195596, 2022). "Recent studies have reported that the depletion of CRABP2 reduced viability and proliferation of tumour cells, implied the regulation of CRABP2 in cell proliferation and cell cycle progression." (PMID 36536476, 2022). "In this study, we used this method and found that cellular retinoic acid binding protein 2 (CRABP2) was the most significantly upregulated protein in the tumor tissues of chemotherapy-resistant patients." (PMID 36195596, 2022). "CRABP2 was significantly upregulated in the tumor tissues of chemoresistant GC patients and was closely related to prognosis." (PMID 36195596, 2022). "Regions 0 and 5 of the cancer overlapped with TM4SF1 + cancer cells (Epi-C0), and regions 1 and 3 of the tumor overlapped mainly with CRABP2 + cancer cells (Epi-C3)." (PMID 36434043, 2022). "The data analysis results showed that the expression of CRABP2 in GC tumor tissues was significantly upregulated (P < 0.001)." (PMID 36195596, 2022). "What makes us feel contradictory and interesting is that FABP5 should be a tumor suppressor in ESCC like CRABP2, with high expression in normal tissues and low expression in tumor tissues." (PMID 34632074, 2021). "Overexpression of CRABP2 inhibited the growth, metastasis, and apoptosis of tumor cells and was closely related to tumor location, TNM stage, invasion depth, and degree of differentiation but the specific mechanism is unclear." (PMID 34632074, 2021). "But our team deemed that it is related to tumor types and specific pathological types, and the expression level and ratio of CRABP2 and FABP5 are expected to serve as valuable biomarkers." (PMID 34632074, 2021). "The monolayer wound healing and transwell assays also confirmed that overexpression of Lats1 reversed the overexpression of CRABP2 results promoting tumor cells invasion and metastasis." (PMID 31419991, 2019). "Resveratrol exerts little inhibitory effect on THJ-11T ATC cells but upregulates Tg and E-cadherin expression and efficiently reverses their RA resistance by activating CRABP2/RAR-mediated tumor suppression signaling." (PMID 29596381, 2018). "The overexpression of CRABP2 is related to advanced stages of this cancer, which indicates the involvement of the RA pathway in tumor progression." (PMID 29378601, 2018). "Reports describe abnormal cellular retinoic acid-binding protein 2 (CRABP2) expression in neoplasms and its correlation with prognostic factors and clinical and pathological characteristics." (PMID 29378601, 2018). "We confirmed cell type-specific expression of CRABP2 in human HGSOC tumours and normal OSE using immunofluorescence, as well as in normal FTECs, fallopian tube HGSOC and omentum HGSOC." (PMID 27561551, 2016). "To further consolidate its antioncogenic role in vivo, we established the tumor-bearing nude mice model by subcutaneously injecting the stably transfected Vector and CRABP2 OE EC109 cells." (PMID 26839961, 2016).
tumor (continued). "As we had shown that CRABP2 regulated cell migration via EMT in vitro, we further examined the expression of Vimentin in CRABP2 OE tumor tissues dissected from the nude mice, in comparison with that in Vector tumor tissues." (PMID 26839961, 2016). "In the study, we have provided sufficient evidence that CRABP2 acts as a tumor suppressor in esophageal squamous tumorigenesis." (PMID 26839961, 2016). "Surprisingly, we found that the expression of Vimentin was strikingly reduced in five of CRABP2 OE tumor tissues, suggesting that CRABP2 was of great possibility to regulate cell metastasis by inhibiting Vimentin expression in vivo." (PMID 26839961, 2016). "In particular, CRABP1 was expressed in the tumor stroma, and CRABP2 and FABP5 were expressed in the sebaceous gland cells, interfollicular epidermis, and hair follicles." (PMID 26503156, 2015). "In contrast, CRABP2 mRNA levels are significantly up-regulated in ER-positive tumors compared to normal and triple-negative tumor tissues." (PMID 26142905, 2015). "Furthermore, an investigation into the expression profile of CRABP2 in LUAD tumor tissues versus normal lung tissues revealed patterns consistent with those observed in plasma." (PMID 39991584, 2025). "Furthermore, CRABP2 has the ability to advance the progression of LUAD by facilitating the G2/M phase transition of LUAD tumor cells and suppressing the apoptosis of LUAD cells." (PMID 39991584, 2025). "In addition, the effect of reducing tumor weight by downregulating CRABP2 was significantly restored after silencing PLAAT4." (PMID 40657374, 2025). "Functional roles are context-dependent, for instance, CRABP2 may act as either tumour suppressor or promoter, and FABP4 exhibits metabolic state dependent effects." (PMID 41149452, 2025). "Our findings suggest that CRABP2 may facilitate the advancement of LUAD by modulating the tumor cell cycle and impeding apoptosis in LUAD cells." (PMID 39991584, 2025). "Furthermore, we delved into the intricate relationship between CRABP2 and the tumor immune microenvironment, immune regulation, and immune checkpoint pathways." (PMID 39991584, 2025). "Furthermore, Immunohistochemical staining further confirmed high expression of CRABP2 within tumor cells, showing notable cytoplasmic accumulation." (PMID 40657374, 2025). "Based on these observations, we postulate that CRABP2 expression could potentially serve as a biomarker for predicting immunotherapy efficacy in multiple cancers, thereby guiding anti-tumor immunotherapy strategies." (PMID 39991584, 2025). "In addition, immunohistochemical analysis of tissue microarrays from patients at our center revealed that Cyto‐CRABP2 has strong predictive value for tumor metastasis, with Nu‐CRABP2 and total‐CRABP2 serving as relatively weaker predictors." (PMID 40305785, 2025). "This study elucidates the potential mechanisms of CRABP2's influence on tumor-immunity in LUAD, offering valuable insights that could pave the way for early diagnosis, precise therapeutic targeting, and immunotherapy strategies of LUAD." (PMID 39991584, 2025). "However, the mechanisms of action for CRABP2 are complex, and the protein can act as both a tumor suppressor and a promoter." (PMID 40305785, 2025). "Given that the crucial roles of PLAAT4 in tumor progression and lipid metabolism, we hypothesized that it plays a vital role in the oncogenic activity of CRABP2." (PMID 40657374, 2025). "The expression of CRABP2 may be related to the heterogeneity of the tumor immune microenvironment, which could affect the response to immunotherapy." (PMID 39991584, 2025). "In addition, the same conclusion was reached in the tissue microarray, and CRABP2 expression was also enhanced in CRC tumor tissues of patients with high RanGAP1 expression." (PMID 38267624, 2024). "Meanwhile, inhibition of CRABP2 expression can significantly reverse tumor drug resistance." (PMID 38195606, 2024).
tumor (continued). "Additionally, the expression level of CRABP2 is positively correlated with the histopathological grade and clinical stage of the tumor." (PMID 38195606, 2024). "CRABP2 has been reported to promote EMT of tumor cells in different tumors." (PMID 38186580, 2023). "Additionally, CRABP2 was found to promote tumor growth in SKCM xenograft mice and positively correlate with infiltration and marker of CAFs in SKCM." (PMID 38186580, 2023). "Subsequently, three different algorithms on the TIMER2 website were used to demonstrate the effect of CRABP2 on CAFs infiltration in TCGA tumor, indicating a positive correlation between CRABP2 and CAFs infiltration in SKCM (spearman’s R: 0.481–0.545, p < 0.05)." (PMID 38186580, 2023). "Furthermore, the expression of TET1 and CRABP2 in tumor tissues of GC patients was positively correlated, as shown by qRT-PCR." (PMID 36195596, 2022). "Moreover, the expression of CRABP2 was increased in the GC tumor tissues of our cohort and the TCGA database." (PMID 36195596, 2022). "Additionally, overexpression of Lats1 reversed the knocking down CRABP2 expression results promoting tumor cells invasion and metastasis by monolayer wound healing and transwell assays." (PMID 31419991, 2019). "Similarly, higher CRABP2 levels were found in tumor tissues of stage III than in stage I patients, and also higher in lymph node metastatic (N1+) than non-metastatic (N0) patients." (PMID 30696915, 2019). "Additionally, the drug combination upregulated PINK1, IRF1, PPP1R15A, CRABP2, SCRN1, LIMA1, and TGFBI; all genes associated with tumor suppression functions in PCa." (PMID 29545934, 2018). "Thus, expression of CRABP2 in tumor Schwann cells makes these cells principally suitable for ATRA treatment." (PMID 29131833, 2017). "Additionally, the biological function assays demonstrated that CRABP2 acted as a tumor suppressor in esophageal squamous carcinogenesis by significantly inhibiting cell growth, inducing cell apoptosis and blocking cell metastasis both in vitro and in vivo." (PMID 26839961, 2016). "Taken together, we considered that CRABP2 might act as a tumor suppressor in esophageal tumorigenesis." (PMID 26839961, 2016). "The data presented so far proposed a model in which patients with ALDH1A2low tumors, who are at high risk for treatment failure might benefit from restoration of RA availability as long as their tumor cells express CRABP2." (PMID 26634247, 2015). "The plasma CRABP2 level may be an indicator of biological aggressiveness of the tumor." (PMID 38915108, 2024). "Abnormal gene expression of CRABP2 has been observed in various tumors and may play an important role in regulating proliferation, apoptosis, invasion, metastasis and other activities of tumor cells." (PMID 38186580, 2023). "CRABP2, an intracellular retinol-binding protein, might contribute to tumor growth and spread." (PMID 37702857, 2023). "In this study, we analyzed the tumor samples of GC patients who received neoadjuvant chemotherapy based on oxaliplatin through quantitative proteomics and identified the potential chemoresistance-related protein cellular retinoic acid binding protein 2 (CRABP2)." (PMID 36195596, 2022). "Thus, CRABP2 acted as a tumor suppressor in esophageal squamous tumorigenesis." (PMID 26839961, 2016). "We found CRABP2 can regulate the occurrence and development of cancer by regulating the LUAD tumor immune microenvironment." (PMID 39991584, 2025). "In conclusion, CRABP2 can regulate the occurrence and development of cancer by regulating the LUAD tumor immune microenvironment." (PMID 39991584, 2025). "High expression of CRABP2 in LUAD inhibits the recruitment of immune effector cells and increases the proportion of immunosuppressive cells, thereby promoting tumor progression." (PMID 39991584, 2025).
tumor (continued). "In summary, the proportional relationship between CRABP2 and FABP5 with tumor progression is still controversial." (PMID 34632074, 2021). "Its biological effects are largely determined by two classical signaling pathways mediated by Cellular retinoic acid binding protein 2 (CRABP2) or Fatty acid-binding protein 5 (FABP5), which results in tumor suppression or tumor promotion." (PMID 31736873, 2019). "Further analysis revealed that resveratrol significantly upregulated CRABP2 expression and reversed the RA tolerance of THJ-11T by opening the RA tumor suppression pathway." (PMID 31736873, 2019). "Since the retinoid binding affinity of the CRABP2-RAR pathway is higher than that of the FABP5-PPARβ/δ pathway, at least a partial ATRA-mediated tumor-suppressive effect is expected in tumors with comparable FABP5 and CRABP2 expression." (PMID 30384831, 2018). "As CRABP2 is the major mediator of cellular ATRA response, its expression in a series of tumor Schwann cells had been analyzed in previous studies." (PMID 29131833, 2017). "CRABP2 and FABP5 were expressed in hair follicles of eyelid skin in both groups, whereas CRABP2 and FABP5 were aberrantly expressed in the SeCC tumor cells." (PMID 26503156, 2015). "CRABP2 and FABP5 were expressed in hair follicles of lid skin in both groups, whereas the CRABP2 and FABP5 were aberrantly expressed in the tumor cells of the sebaceous glands." (PMID 26503156, 2015). "Moreover, CRABP2 and Eukaryotic Translation Initiation Factor 3 Subunit D (EIF3D) were found to promote tumor growth by activating FAK through the Integrin β1/FAK/ERK and GRP78-related pathways, respectively." (PMID 41148856, 2025). "CRABP2, KRT14, and CEBPA expressions were significantly increased in STAS tumor cells." (PMID 40786043, 2025). "Therefore, we evaluated the tumor infiltration levels of CD8+ T cells, CD4+ T cells, neutrophils, and macrophages in LUAD samples with varying somatic copy number alterations of CRABP2." (PMID 39991584, 2025). "To better understand the role of CRABP2 in CRC in vivo, we next analyzed paired samples from CRC patients and observed a significant upregulation of CRABP2 mRNA in CRC samples relative to non‐tumor tissue." (PMID 40305785, 2025). "Notably, pharmacological targeting of CRABP2 using SNIPER-11 reduces cholesterol content, suppresses AKT activation, and sensitises tumours to gemcitabine both in vitro and in patient-derived xenograft models." (PMID 41149452, 2025). "Lastly, we performed immunoblot analysis confirming CRABP2 expression in the nucleus and cytoplasm of tumor cells from patients with and without CRLM, respectively." (PMID 40305785, 2025). "Since the role of CRABP2 gene in tumor immunotherapy has not been elucidated, we conducted a correlation analysis between the expression of CRABP2 and the efficacy of immunotherapy." (PMID 38186580, 2023). "Additionally, we found a lower proportion of primary OCCC tumor tissues of OCCC expressing WFDC2 and CRABP2 compared than was found in HGSC tissues." (PMID 37525249, 2023). "Immunohistochemistry was applied to detect the protein content in tumor tissues, and the result indicated that CRABP2 level is higher in cancer tissues than their counterpart normal ovary tissues and borderline tumors." (PMID 35578123, 2022). "CRABP2 has been known as the central player of RA tumor suppression, and, in contrast, FABP5 has been known as an RA tumor promotion signaling; these molecules function by delivering RA to its corresponding nuclear receptors, i.e., RAR-β and PPAR-β/δ, respectively." (PMID 29596381, 2018). "Taken together, CRABP2 in esophageal tumorigenesis acted as a tumor suppressor not only by inhibiting cell proliferation, but also by blocking cell metastasis via EMT process." (PMID 26839961, 2016). "In our data, the CRABP1 protein was not expressed strongly in the tumor cells of SeCC cases, whereas the CRABP2 protein was overexpressed in the tumor cells of SeCC cases." (PMID 26503156, 2015).
tumor (continued). "Notably, in the analysis of metastasis characteristics, the expression level of CRABP2 in metastasis-positive tumor tissues was 1.9 times higher than that in non-metastatic groups (P = 0.009)." (PMID 40657374, 2025). "In oesophageal squamous cell carcinoma (ESCC), CRABP2 expression is significantly downregulated in tumour tissues relative to normal epithelium with the reduction correlating with advanced TNM stage, poor differentiation, tumour infiltration, and worse overall survival." (PMID 41149452, 2025). "Here, we firstly evaluated the expression of CRABP2 at both mRNA and protein levels and showed that it was remarkably downregulated in clinical ESCC tissues and closely correlated with the occurrence position, pathology, TNM stage, size, infiltration depth and cell differentiation of the tumor." (PMID 26839961, 2016). "In accordance with the notion that the tumor suppressing activity of KLF2 is exerted at least in part by controlling RA signaling, ectopic expression of this factor, similarly to direct alteration of the FABP/CRABP2 ratio, converted RA from a pro- to an anti-proliferative agent." (PMID 26416422, 2015). "All of CRABP2, DHCR24, and AK4 showed cytoplasmic staining of tumor cells, but no staining was evident in the stroma." (PMID 37004157, 2023).